SNORD116-11 (small nucleolar RNA, C/D box 116-11)
Synonyms: HBII-85-11
Gene: Small nucleolar RNA gene on chromosome 15 (25,075,929 to 25,076,020, forward strand). Ensembl gene ENSG00000206609.
Gene Ontology:
Biological process: RNA processing
Cellular component: nucleolus
Homologues: Orthologues: chimpanzee SNORD116 (99% identical), macaque SNORD116 (90% identical), guinea pig SNORD116 (83% identical), guinea pig SNORD116 (80% identical). Paralogues in human: SNORD116-15 (89% identical), SNORD116-16 (89% identical), SNORD116-20 (89% identical), SNORD116-22 (89% identical), SNORD116-17 (88% identical), SNORD116-19 (88% identical), SNORD116-23 (88% identical), SNORD116-14 (87% identical), SNORD116-18 (87% identical), SNORD116-21 (87% identical), SNORD116-24 (86% identical), SNORD116-12 (85% identical), and 20 more.